ENSG00000201003
Synonyms: LOC124900439
Gene: Small nucleolar RNA gene on chromosome 1 (53,771,018 to 53,771,153, reverse strand). Ensembl gene ENSG00000201003.
Gene Ontology:
Biological process: RNA processing
Cellular component: nucleolus
Homologues: Orthologues: mouse Gm54509 (79% identical), rat Gm50450 (77% identical). Paralogues in human: SNORA58 (91% identical), SNORA58B (85% identical).